EFHC1 (EF-hand domain containing 1)
Description:
Microtubule inner protein (MIP) part of the dynein-decorated doublet microtubules (DMTs) in cilia axoneme, which is required for motile cilia beating. Microtubule-associated protein which regulates cell division and neuronal migration during cortical development. Necessary for radial and tangential cell migration during brain development, possibly acting as a regulator of cell morphology and process formation during migration. May enhance calcium influx through CACNA1E and stimulate programmed cell death.
Synonyms: FLJ10466; RIB72; POC9; EJM1; dJ304B14.2; formerly EJM
Tractability: Small molecule: a structure with a bound ligand is known. PROTAC: ubiquitination databases record sites on it.
Gene: Protein-coding gene on chromosome 6 (52,362,123 to 52,529,886, forward strand). Ensembl gene ENSG00000096093.
Subcellular location: Cytoplasm, cytoskeleton, cilium axoneme; Cytoplasm, cytoskeleton, flagellum axoneme; Cytoplasm, cytoskeleton, microtubule organizing center, centrosome; Cytoplasm, cytoskeleton, spindle; Cytoplasm, cytoskeleton, spindle pole
Subcellular location (Human Protein Atlas): End piece; Mid piece; Plasma membrane; Principal piece; Cytosol; Equatorial segment
Gene Ontology:
Molecular function: alpha-tubulin binding; protein binding; calcium ion binding
Biological process: cerebral cortex cell migration; mitotic cytokinesis; mitotic spindle organization; regulation of cell division; cilium-dependent cell motility; flagellated sperm motility
Cellular component: axonemal microtubule; centrosome; mitotic spindle; spindle pole; axonemal A tubule inner sheath; axoneme; neuronal cell body; sperm flagellum; spindle
Genetic constraint (gnomAD): Loss-of-function variants: 53 observed, 73.51 expected, observed/expected ratio (o/e) 0.72, 90% interval 0.58 to 0.91. The upper end of that interval is the gene's LOEUF score, 0.91, which puts it in group 3 of 6, group 1 being the genes least tolerant of losing a copy. Missense variants: 739 observed, 842.48 expected, observed/expected ratio (o/e) 0.88, 90% interval 0.82 to 0.93. Synonymous variants: 256 observed, 295.62 expected, observed/expected ratio (o/e) 0.87, 90% interval 0.78 to 0.96.
Gene-disease validity (ClinGen):
ClinGen rates the evidence that EFHC1 causes each of these diseases.
epilepsy (autosomal dominant): Refuted. A brain disorder characterized by episodes of abnormally increased neuronal discharge resulting in transient episodes of sensory or motor neurological dysfunction, or psychic dysfunction.
Homologues: Orthologues: macaque EFHC1 (98% identical), chimpanzee EFHC1 (96% identical), dog EFHC1 (90% identical), pig EFHC1 (89% identical), rabbit EFHC1 (88% identical), mouse Efhc1 (85% identical), rat Efhc1 (84% identical), guinea pig EFHC1 (78% identical), tropical clawed frog efhc1 (55% identical), zebrafish efhc1 (44% identical), Caenorhabditis elegans efhc-1 (18% identical). Paralogues in human: EFHC2 (36% identical), EFHB (14% identical).
Diseases named in the same sentence as EFHC1 in open-access papers:
EFHC1 is named in the same sentence as 13 diseases in open-access papers, as found by Europe PMC text mining. Sharing a sentence is not in itself a finding about the gene and the disease. The quoted sentences say what the papers report.
juvenile myoclonic epilepsy (14 papers, 2012 to 2026). "Mapping of 6p12–11 loci in a large Belize family with JME revealed a common EFHC1 polymorphism present in higher frequency than in healthy individuals, cosegregating with juvenile myoclonic epilepsy." (PMID 33969125, 2021). "TRPM2 is reported to have molecular and functional interaction with EF-hand motif-containing protein (EFHC1), mutation in which causes juvenile myoclonic epilepsy (JME) via neuronal apoptosis." (PMID 32963700, 2020). "It is known that EFHC1 Arg294His is a genetic cause of childhood absence epilepsy and juvenile myoclonus epilepsy." (PMID 31875159, 2019). "Moreover, CARP4 is orthologous to the human EF Hand Containing protein EFHC1 (BLASTP E-value = 5E-55) that is linked to Juvenile Myoclonic epilepsy and is believed to be part of the structure of cilia." (PMID 37475965, 2023). "A human homolog of RIB72, EFHC1, is linked to juvenile myoclonic epilepsy." (PMID 34969817, 2022). "Interestingly, a human homologue of CARP4, EFHC1, has been shown to be a component of axonemes and cilia, with mutations in EFHC1 being implicated in juvenile myoclonic epilepsy." (PMID 23877697, 2013). "In juvenile myoclonic epilepsy (JME), however, there is a mutation in EFHC1." (PMID 36902145, 2023). "Pathogenic variants in EFHC1 have been reported in patients with juvenile myoclonic epilepsy (JME)." (PMID 33328576, 2020). "To shed light into their functions, we studied EFHC1, an evolutionarily conserved protein required for motile cilia function and linked to a common form of inherited epilepsy in humans, juvenile myoclonic epilepsy (JME)." (PMID 30810526, 2019). "TRPM2 may be a channel protein of interest in juvenile myoclonic epilepsy as EFHC1, the candidate gene for this disease, potentiates TRPM2 in ROS-mediated neuronal death." (PMID 36902145, 2023). "EFHC1 is associated with ciliary signalling in both human cells and C. elegans, but its disruption in humans results in juvenile myoclonic epilepsy, whose aetiology could potentially result from non-motile cilia dysfunction." (PMID 36329026, 2022). "Increasingly, molecular genetic studies have identified defects in non-ion channel genes in common IE, such as the calcium sensors EFHC1 in juvenile myoclonic epilepsy (JME) and CASR in idiopathic generalized epilepsy (IGE)." (PMID 23209433, 2012). "In patients with juvenile myoclonic epilepsy, several individual loci are involved, of which GABRA1, GABRD, EFHC1, BRD2, CASR, and ICK with complex inheritance are considered to be the most pathogenic." (PMID 39513854, 2024).
epilepsy (7 papers, 2015 to 2025). "WES focusing on epilepsy genes revealed a heterozygous EFHC1 variant, p.Arg294His, previously implicated in myoclonic epilepsy." (PMID 41282474, 2025). "For example, the following genes were previously thought to be associated with epilepsy: EFHC1, SCN9A, CLCN2, GABRD, SRPX2 and CACNA1H." (PMID 28558813, 2017). "EFHC1 mutations may be considered pleiotropic due to their involvement in various epilepsy phenotypes." (PMID 33969125, 2021). "The mechanism by which EFHC1 mutations cause epilepsy is unclear however, as the protein encoded by this gene has been linked to several effects that could damage brain development." (PMID 25875328, 2015). "While several neuronal roles have been proposed for EFHC1, it remains unclear how mutations in EFHC1 lead to epilepsy." (PMID 30810526, 2019). "First, EFHC1 is the only gene in which mutations were found in many unrelated families with JME across the world, and second, no ion channel protein is coded by it as usually the case in epilepsy." (PMID 33969125, 2021). "The only other known non-channel, non-receptor epilepsy gene related to JME is EFHC1/Myoclonin1, mutations in which have been reported in 3 to 9% of JME patients worldwide." (PMID 25875328, 2015). "Although EFHC1 dysfunction impairs motility of ependymal cilia in mice, the accompanying ventricle enlargement does not correlate with epilepsy." (PMID 30810526, 2019).
asthma (3 papers, 2015 to 2025). "A multi-stage GWAS study in children with childhood AD and asthma found new genetic loci (rs9357733 positioned in EFHC1 on chromosome 6p12.3 and rs993226 between TMTC2 and SLC6A15 on chromosome 12q21.3) that were specific for AD-asthma march phenotype." (PMID 35455494, 2022).
allergic disease (2 papers, 2015 to 2025). An immune response that occurs following re-exposure to an innocuous antigen, and that requires the presence of existing antibodies against that antigen. "We identified seven genome-wide significant loci, of which two susceptibility loci, in EFHC1 on chromosome 6p12.3 and between TMTC2 and SLC6A15 on chromosome 12q21.3 were associated with allergic disease for the first time." (PMID 26542096, 2015).
ciliopathy (2 papers, 2020 to 2024). A genetic disorder of the cellular cilia or the cilia anchoring structures, the basal bodies, or of ciliary function. "The related mammalian protein EFHC1 (EF-hand–containing protein 1)/myoclonin is a microtubule-associated protein identified as a ciliopathy protein linked to myoclonic epilepsy and present in motile cilia; however, it is not present in mammalian neurons." (PMID 38182160, 2024).
Myoclonus (1 paper, 2019). Very brief, involuntary random muscular contractions occurring at rest, in response to sensory stimuli, or accompanying voluntary movements. "At adult stages, both Efhc1-Het and Efhc1-KO mice developed spontaneous myoclonus and both genotypes have a greater sensitivity to PTZ induced seizures." (PMID 31611775, 2019).
partial epilepsies (1 paper, 2015). "Mutations in both the EFHC1 and CPA6 genes have been found in patients with generalized and partial epilepsies." (PMID 25875328, 2015).
EFHC1 also shares sentences with these, for which no sentence is quoted: eczema (2 papers); myoclonic epilepsy (2); encephalitis (1); idiopathic generalized epilepsy (1); neurodevelopmental disorder (1); tumor (1).